BCL2 (BCL2 apoptosis regulator)
Diseases named in the same sentence as BCL2 in open-access papers (continued):
Sharing a sentence is not in itself a finding about the gene and the disease.
lymphoma (continued). "The expression of BCL-2 in lymphomas has been widely reported, the t (14:18) translocation generates a constitutive expression of BCL-2 derived from the juxtaposition of BCL-2 with the immunoglobulin heavy chain promoter in follicular lymphoma, and in 30% diffuse large B-cell lymphoma." (PMID 35216310, 2022). "Recently, a group of natural products (Rocaglates) and their synthetic derivatives have been emerging as promising therapeutical agents for the treatment of MYC-associated lymphoma, especially those Double Hit lymphoma with concurrent MYC and BCL2 dysregulation." (PMID 35303910, 2022). "Moreover, combining PRMT5 inhibition with MSI2 or BCL-2 inhibitors blocks the translation of key drivers of lymphoma, c-MYC and BCL-2, inhibiting cell growth." (PMID 36167829, 2022). "Also, restoration of HEVM ectodomain by soluble HVEM protein or HVEM-producing and CD19-targeted CAR-T cells were tumor-suppressive in MYC + /BCL2 + DLBCL cell lines and BCL2 overexpressing lymphoma xenograft model, respectively." (PMID 35303910, 2022). "Bcl-2 is frequently overexpressed in lymphomas and leukemias." (PMID 36555165, 2022). "In addition, all lymphomas developed in OPN-/-Faslpr/lpr mice were of the ABC-DLBCL type based on the expression of BCL2, C-MYC, IRF4 and of high proliferation rate (Ki67), in absence of BCL6." (PMID 36503430, 2022). "These included one 81-year-old patient in PR after three cycles of treatment with venetoclax that converted to CR at cycle 9 and was maintained 24 months from the beginning of treatment; this patient had PTCL-NOS histology with 50% BCL2 lymphoma cell positivity." (PMID 34938664, 2021). "For example, ABT-737, an acrylsulfonamide-based pan Bcl-2 inhibitor that binds to Bcl-xL, Bcl-2 and Bcl-w, was shown to exert potent single-agent activity in leukemia and lymphoma cells lines as well as synergistic effect in combination with other anticancer drugs in leukemia and solid tumors." (PMID 33523262, 2021). "Next, we directly examined how eIF4A inhibition affects translation in MYC+/BCL2+ lymphomas." (PMID 33562682, 2021). "RCHOP and venetoclax should be effective in high-grade lymphomas that express BCL2 protein, are not class B, and co-depend on BCL2 and MCL1 (53% of our diagnostic DLBCL samples)." (PMID 33670870, 2021). "Pathogenic variants were obvious in some of the most commonly affected genes in lymphomas, such as BCL2, MYD88, NOTCH2, EZH2, and CD79B, and most of them could be identified in matched LB-originated cfRNA." (PMID 34204385, 2021). "Lymphomas bearing all three translocations (MYC+/BCL2+/BCL6+) are known as triple-hit lymphomas." (PMID 34372899, 2021). "Moreover, overexpression of BFL-1 enhances the resistance of c-MYC- and BCL2-expressing double-hit lymphomas to venetoclax, while its downregulation sensitizes them to apoptotic stimuli." (PMID 34576319, 2021). "The expression of HSP-70, c-Myc, Bcl-2, Mcl-1, xIAP, and Bcl-xL, as well as other molecules, such as phosphatidylinositol, ERK, MAPK, chemokines, cell surface receptors, and G proteins in lymphoma cell-derived EVs, has also been linked to resistance to immunotherapy." (PMID 33805807, 2021). "Indeed, FYN-TRAF3IP2-dependent lymphoma cells display exquisite sensitivity to the BCL-XL, BCL2 and BCL-W (encoded by Bcl2l2) inhibitor ABT-263." (PMID 34140493, 2021).
lymphoma (continued). "With the success of small-molecule inhibitors targeting anti-apoptotic BCL-2 proteins for the treatment of lymphoma, we can now envision the use of inhibitors of apoptosis with exquisite selectivity for BCL-2 family protein regulation of neuronal apoptosis in the treatment of nervous system disease." (PMID 33162554, 2021). "The most recent revision of lymphoid neoplasms by the WHO recognized a more aggressive, high-grade B-cell lymphoma subtype with a worse prognosis, the ‘double-hit’/‘triple-hit’ (DH/TH) lymphoma, which is characterized by MYC rearrangements that are associated with BCL2 and/or BCL6 rearrangements." (PMID 34207773, 2021). "Similarly, expression of NRF2E79V in the MYC+/BCL2+ SuDHL-6 lymphoma cells protects them against silvestrol treatment." (PMID 33562682, 2021). "Ezh2Y641F Bcl2+ chimeric mice led to early lymphoma development in 70% of mice at 111 days (vs 20% in mice overexpressing Ezh2WTBcl2+ and none in the Bcl2 control at that stage), characterized by enlarged spleen and liver and resembling morphologically to DLBCL with centroblastic morphology." (PMID 34335584, 2021). "DLBCL, the most prevalent lymphoma subtype, can be divided into BCL2 and MCL1-dependent categories." (PMID 34576319, 2021). "The application of a multitarget BCL2/BCL6 FISH in lymphomas could improve the molecular diagnosis in terms both of time and costs." (PMID 33768318, 2021). "Unlike the rest of B-NHL, the level of Bcl-2 expression in Burkitt lymphoma is low or undetectable, which has been used as part of the diagnostic algorithm for this subtype of lymphoma." (PMID 33412518, 2021). "Preclinical data suggest that combining PI3K and BCL2 inhibitors, such as venetoclax, may have therapeutic value by sensitizing lymphoma cells to BCL2 inhibitors while suppressing acquired resistance." (PMID 35582375, 2021). "Due to the particularly poor outcomes of patients with c-Myc translocation shown in some retrospective studies, these patients were reclassified as high-grade lymphoma with c-Myc translocation and bcl-2 and/or bcl-6 translocation in the 2016 WHO classification of lymphatic tumors." (PMID 32843697, 2020). "Here, we investigated whether ectopic expression of c-MYC and BCL2 in different stages of B cells could lead to lymphoma and generate a mouse model for DEL." (PMID 32695674, 2020). "Data on gene rearrangement are limited but suggested that the presence of the IGH/IGK rearrangement with BCL2 or MYC expression might play a significant role in lymphoma genesis." (PMID 33071959, 2020). "Thus, in light of the current WHO classification, the diagnosis was revised to high-grade B-cell lymphoma with MYC and BCL2 rearrangement, Burkitt morphology (so-called “double-hit” lymphoma)." (PMID 33339535, 2020). "MYC/BCL2 DH lymphomas represent approximately 60%‐85% of all cases of DH lymphoma." (PMID 32459397, 2020). "The lymphoma cells often show expression of Bcl-2 and ~50% cases can be positive for CD43." (PMID 33322508, 2020). "However, few studies have investigated OCT-1 and BCL-2 gene in malignant lymphoma in the same cohort." (PMID 33121489, 2020). "Besides BCL-2 translocation and amplification, BCL-2 gene rearrangement is reported in double-hit lymphomas, which represent ~10% of DLBCL." (PMID 33139702, 2020). "Given the highly proliferative nature of DLBCL with MYC/BCL2-DH, these high-grade lymphoma cells may frequently efface the low-grade FL lesion, potentially leading to its underdetection." (PMID 31844144, 2020). "Moreover, SA-β-gal activity reached much higher levels in ADR-exposed LSD1;bcl2 lymphomas if co-treated with the LSD1 inhibitor 2-PCPA-1a in vitro, similarly to the high SA-β-gal activity induced by CTX exposure under 2-PCPA-1a co-treatment in vivo." (PMID 32686676, 2020). "Importantly, the frequency of these alterations, as well as the extent of BCL2 mRNA and protein expressions, are substantially different in distinct lymphoma subtypes." (PMID 32290241, 2020).
lymphoma (continued). "DLBCL cases with dual rearrangement of MYC and BCL2 and/or BCL6, frequently named “double-hit” lymphomas, are associated with significantly shorter survival and have been reclassified as a new group of lymphomas by the World Health Organization." (PMID 33087075, 2020). "Based on the results of in vitro study, BET inhibitors alone or in combination with BCL-2 inhibitors may provide therapeutic potential for patients with MYC-dependent lymphomas in the future." (PMID 33317571, 2020). "Interestingly, antilymphoma activity of hippuristonal was blocked by overexpression of the anti-apoptotic proteins BCL2 or MCL1 and hippuristonal synergized with the BCL2 inhibitor ABT-737 to induce of apoptosis of MYC lymphoma cells in vitro." (PMID 32924027, 2020). "The establishment of this model may provide a valuable tool to study the pathogenesis and treatment of c-MYC and BCL2 double-expressor lymphoma." (PMID 32695674, 2020). "MCL-1 has sequence similarity with BCL-2 and involved innormal development in lymphoma." (PMID 31285648, 2019). "In addition, they determined Bcl-2 expression also in 20 various non-Hodgkin lymphomas and in Hodgkin lymphomas, with the maximum number of six cases per lymphoma type." (PMID 31146399, 2019). "Moreover, OTSSP167 demonstrated potent in vitro and in vivo anti-lymphoma activity, which was further enhanced by the Bcl-2 inhibitor venetoclax." (PMID 31740676, 2019). "In addition, OTSSP167 also sensitized the lymphoma cells to the clinically relevant Bcl-2 inhibitor venetoclax by strongly reducing Mcl1 levels." (PMID 31740676, 2019). "Immunohistochemical analysis revealed that large cells in the germinal centers and lymphocytes in the perifollicular/marginal zone were positive for the pan-B-cell antigens CD20 and CD79a and positive for Bcl-2, also supporting the neoplastic nature of this lymphoma lesion." (PMID 31439011, 2019). "Thus, constitutive IP3 signaling in lymphoma and leukemia cells is not only important for cancer cell survival, but also represents a vulnerability, rendering cancer cells dependent on Bcl-2 to limit IP3R activity." (PMID 29899382, 2019). "Both germinal center B cell (GCB) and double-expressor (MYC+/Bcl2+) lymphomas were found in 21%." (PMID 31189479, 2019). "We describe a case of composite lymphoma consisting of chronic lymphocytic leukemia/small lymphocytic lymphoma (CLL/SLL), follicular lymphoma (FL) and high-grade lymphoma with MYC and BCL2 rearrangements (formerly and more colloquially denoted “double-hit” lymphoma)." (PMID 29793519, 2018). "There was no apparent association of sensitivity with either ABC or GCB lymphoma subtypes or the presence or absence of a BCL2 translocation." (PMID 30067771, 2018). "Furthermore, panobinostat enhanced the efficacy of the BCL2 inhibitor S55746 in several lymphoma cell lines." (PMID 30404918, 2018). "In a recent study, a subset of lymphoma cell lines expressing BCL-2 protein were resistant to venetoclax, resulting from acquired mutations in BCL-2 and the pro-apoptotic protein BAX or a phosphorylation event on BCL-2 that prevented venetoclax from binding, thereby blocking apoptosis." (PMID 30671383, 2018). "The finding of BCL2 in a MYC-related miRNAs targets network associated to BL, lymphoma in which BCL2 protein expression is absent, should not surprise." (PMID 30038718, 2018). "BCL-2 also enhances the role of other oncogenes and induces lymphoma." (PMID 30666200, 2018). "Given that apoptosis blockage is a key oncogenic mechanism in lymphoid malignancies, and that BCL-2 overexpression is a common finding in leukemias and lymphomas, many antagonists of anti-apoptotic BCL-2 have been developed and investigated for the treatment of hematological neoplasms." (PMID 29747654, 2018). "BCL2 is a promising therapeutic target for treatment of cancer, including lymphomas." (PMID 30404918, 2018).
lymphoma (continued). "Finally, allotransplantation of either splenocytes or cell-containing ascites from lymphoma-bearing TRAF3/BCL2 mice into SCID/NOD immunodeficient mice showed efficient transfer of the parental expanded B-cell clones." (PMID 30687320, 2018). "The level of Bcl-2 was associated with chemoresistance in lymphoma cell lines, but not in leukemic, ovarian and lung cancer cell lines." (PMID 29515335, 2018). "However, recent discoveries and low complete response rates in clinical trials with targeted therapy against BCL-2 in lymphoma reveal significant gaps in knowledge remain." (PMID 30671383, 2018). "In addition, gene expression profiling of MYC+BCL2–BCL6+ lymphoma cells has shown them to be different from MYC+BCL2+BCL6– lymphoma cells." (PMID 30323893, 2018). "Therefore, DHL defined cytogenetically by c-MYC and BCL2 rearrangements comprise both de novo and secondary lymphomas transformed from FL." (PMID 28379189, 2017). "Translocation or amplification of the BCL2 gene occurred in 20-30% of cases of reported lymphomas." (PMID 28209136, 2017). "In this study, we explored the anti-tumor effects of the GSK-3β inhibitor, 9-ING-41, in lymphoma cell lines as a single agent and in combination with novel agents comprising BCL-2 inhibitor (Venetoclax), CDK-9 inhibitor (BAY-1143572) and p110δ-PI3K inhibitor (Idelalisib)." (PMID 29383130, 2017). "In addition, molecular profiling has identified genetic NHL signatures which predict poor prognoses e.g., double-hit lymphomas displaying aberrant expression of Bcl-2, c-Myc, and/or Bcl-6." (PMID 28416758, 2017). "This indicates the important role of Bcl-2 and Bax in biological behavior of lymphomas." (PMID 29531548, 2017). "Importantly, the combination was also effective against “double-hit” lymphoma cell lines which overexpress both c-Myc and Bcl-2." (PMID 28416758, 2017). "BCL2 promotes cell survival and, in combination with c-MYC expression, confers both proliferation and survival advantages in lymphoma cells, which is part of the underlying biological basis for the more aggressive clinical behavior of the double-expressor lymphomas." (PMID 28379189, 2017). "While still correlative at this point, our data suggest that inhibition of BCL-xL along with inhibition of BCL-2 and MCL-1 may be required for inducing response in a subset of patients with high-risk lymphomas." (PMID 29269870, 2017). "While this interest has resulted in advances in treatment of hematogenous cancers, particularly in the inhibition of Bcl-2 and Bcl-xL in lymphoma, effective inhibitor treatments of solid tumors remains a challenge, particularly the effective targeting of Mcl-1." (PMID 28423654, 2017). "Moreover, untreated and Bcl-2-transfected lymphoma cells were even capable of significantly upregulating the expression of Tnf by M(IFN-γ/LPS) macrophages." (PMID 28157210, 2017). "Moreover, overexpression of either BCL-2 or BCL-XL has been reported to abrogate the pro-apoptotic effects of ouabain in a lymphoma cell line." (PMID 27047392, 2016). "BCL-2 is one of the major pro-survival proteins that has an essential function in normal immunity and whose constitutive expression leads to the development of lymphomas." (PMID 27462919, 2016). "In mice, expression of BCL2 in the hematopoietic compartment has been described to result in glomerulonephritis with an incidence of 15 - 25% at 40 weeks and in the development of lymphomas with an incidence of 37 - 50% at 18 months of age." (PMID 26919255, 2016). "Eμ-Myc mice are immunocompetent and cooperate with Eμ-BCL2 mice in a model of double-hit lymphoma." (PMID 27566574, 2016). "Consequently, we showed that once BCL6 activity is suppressed, additional targeting of resistance mechanisms such as BCL2/BCL-XL/MCL1 provides superior anti-lymphoma effect." (PMID 26657288, 2016).
lymphoma (continued). "ABT-737 binds Bcl-2 and Bcl-XL with high affinity and has shown single-agent efficacy against multiple cell lines as well as in combination with standard therapy in human leukemia and multiple myeloma models, lymphoma, melanoma, cholangiocarcinoma or HNSCC." (PMID 26934442, 2016). "Although BCL6 is known to repress tumor checkpoint genes to support lymphoma cell growth, it could also directly repress BCL2 and BCL2L1 (BCL-XL)." (PMID 26657288, 2016). "We recently reported that the interaction of Bcl-2 and Rac1 was localized at the mitochondria, and that mono-site phosphorylation of Bcl-2 at serine 70 (Bcl-2pSer70) stabilized its anti-apoptotic activity and was a poor prognostic indicator in human lymphomas." (PMID 26430964, 2015). "Recently, increasing attention has been given to a subset of mature B-cell lymphomas with both MYC and BCL2 rearrangements, which have been defined as “double hit” lymphomas (DH lymphomas) because of their aggressive clinical course and resistance to conventional chemotherapy." (PMID 26517511, 2015). "However, our study showed similar reduced disease latency with either Myc alone (lymphoma) or Myc/Bcl-2 (leukemia)." (PMID 26338970, 2015). "Furthermore, as a potential translational correlative, extracellular acidosis induced Bcl-2/Bcl-xl level elevation, sensitizing lymphoma/leukemia cell lines to killing by the BH3-mimetic, ABT-737." (PMID 25984552, 2014). "The reason of Bcl-2 overexpression may due to chromosomal translocations, gene amplification, epigenetic regulation and so on in lymphoma." (PMID 25006537, 2014). "Thus, we analyzed 46 B-NHL samples with known karyotypes spotted on TMAs for hallmark lymphoma-associated translocations of the IGH-, BCL2, BCL6- and MYC-genes." (PMID 24733537, 2014). "AK024118 is located within the intron of BCL2 which is a known driver of lymphoma." (PMID 25288503, 2014). "Also, the sensitivity of lymphoma cell lines to Bcl-2 antagonism is directly related to the amount of Bcl-2 primed with Bim." (PMID 23431463, 2013). "Moreover, fluvastatin greatly increased the ratio of Bax and Bcl2 in lymphoma cells in a dose-dependent manner." (PMID 24209962, 2013). "Among these, Bcl-2, Bcl-XL, and Mcl-1 are frequently overexpressed in lymphomas." (PMID 23431463, 2013). "Overexpression of Bcl-2 is common in leukemias and lymphomas." (PMID 23431463, 2013). "Furthermore, translocations and mutations cause overexpression of oncogenes like BCL2, BCL6 and MYC in lymphoma cells." (PMID 23049692, 2012). "BCL2 deregulation is often observed in lymphomas, as in the case of follicular lymphoma." (PMID 22593768, 2012). "Interestingly, in the original paper describing a role for Notch1 in conferring GC resistance, overexpressing ICN in AKR1010 lymphoma cells led to the induction of Bcl-2." (PMID 22319533, 2012). "After interaction with BAFF-R and other receptors, BAFF activates NF-κB, which leads to the resistance to apoptosis of lymphoma B cells by upregulation of the antiapoptotic proteins Bcl-2, Bcl-xL, and Mcl-1 and downregulation of proapoptotic proteins such as Bax." (PMID 23272079, 2012). "Overexpression of BCL-2 and associated anti-apoptotic proteins Bcl-xL, Mcl-1, and BCL-W occurs in substantial subsets of common cancer types that include pancreatic, ovarian, lymphoma, multiple myeloma, lung adenocarcinoma, prostate adenocarcinoma, etc." (PMID 21760983, 2011). "Moreover, the presence of combined MYC dysregulation, and BCL2 upregulation at diagnosis already predicted a very aggressive clinical course with rapid transformation into a high-grade lymphoma." (PMID 21736761, 2011). "Thus, we had at our disposal two lymphosarcoma models displaying MDR: the MDR of RLS40 is mdr1b/1a-associated and the MDR of RLS tumor is predominantly bcl-2-associated." (PMID 20470373, 2010). "Also, preclinical data from lymphoma cell lines and primary tumor samples indicate high efficacy of Bcl-2 inhibitor ABT-737 against lymphoma." (PMID 20815894, 2010).